RN7SKP16 (RN7SK pseudogene 16)
Gene: Miscellaneous RNA gene on chromosome 1 (33,336,566 to 33,336,864, reverse strand). Ensembl gene ENSG00000222112.
Homologues: Orthologues: chimpanzee 7SK (99% identical), mouse Gm54579 (22% identical). Paralogues in human: RN7SKP9 (77% identical), 7SK (76% identical), RN7SKP211 (76% identical), RN7SKP176 (75% identical), RN7SKP71 (75% identical), RN7SKP203 (75% identical), RN7SKP47 (75% identical), RN7SKP189 (75% identical), RN7SKP255 (75% identical), RN7SKP243 (74% identical), RN7SKP79 (74% identical), RN7SKP25 (74% identical), and 284 more.